TLR4 (toll like receptor 4)
Diseases named in the same sentence as TLR4 in open-access papers (continued):
Sharing a sentence is not in itself a finding about the gene and the disease.
Hypertension (continued). "TLR4 activation was recently demonstrated to be involved in activation of the RAS system induced by uric acid in adipose tissue, causing hypertension and higher expression levels of inflammatory cytokines." (PMID 37983238, 2023). "In the cardiac system, the TLR4/Myd88/NF-κB pathway has a regulatory role in hypertension and a protective effect on the heart." (PMID 38259289, 2023). "In a model of hypertension, male SD rats treated with a TLR4 inhibitor showed a significant reduction in myocardial inflammation and expression of iNOS." (PMID 37239362, 2023). "Previously, our laboratory showed that centrally blocking TLR4 improved cardiac function as well as attenuated myocardial inflammation in genetic and angiotensin II-induced hypertension animal models." (PMID 37034342, 2023). "Vasodilation, vascular inflammation, and hypertension were improved after probiotics supplementation, with these changes being attributed to LPS activation of endothelial toll-like receptor 4 (TLR4) in probiotics." (PMID 37465757, 2023). "Further evidence has shown that TLR4 protein expression is increased in the hearts of individuals with diagnosed hypertension." (PMID 37034342, 2023). "In cardiomyocytes, Ang II-induced TLR4 activation of NF-κB in a MyD88dependent manner increases release of proinflammatory cytokines and further results in inflammation and hypertension." (PMID 37034342, 2023). "Together, this data revealed a protective role for cardiomyocyte-specific deletion of TLR4 against Ang II-induced hypertension and cardiac dysfunction through inhibition of proinflammatory cytokines." (PMID 37034342, 2023). "To conclude, our study reveals an important role for cardiomyocyte specific deletion of TLR4 in protection from Ang II-induced hypertension by reducing cardiac hypertrophy, fibrosis, and blunting inflammation." (PMID 37034342, 2023). "In this study, we build upon these findings and focus specifically on TLR4 inhibition in cardiomyocytes, the major contractile cells of the heart in Ang II-induced hypertension." (PMID 37034342, 2023). "Of the known 13 TLRs, TLR4 has been extensively studied within hypertension and has been shown to contribute to the progression of inflammatory responses in the etiology of the disease." (PMID 37034342, 2023). "Studies suggest that Hcy induces hypertension by promoting toll-like receptor 4 (TLR-4-driven) chronic vascular inflammation and mitochondria-mediated cell death." (PMID 37039942, 2023). "TLR4 signaling is known to be the key type of pro-inflammatory signaling in the induction of hypertension and periapical lesions." (PMID 36675104, 2023). "To confirm these findings in Ang II-induced hypertension, we measured TLR4 gene and protein expression in the heart and showed a significant elevation in TLR4." (PMID 37034342, 2023). "As an initial step to study the contribution of the TLR4 pathway in the development of Ang II-induced hypertension and cardiac remodeling, the present study was conducted only in male mice." (PMID 37034342, 2023). "Previous studies from our lab demonstrated that central TLR4 blockade reduced cardiac TLR4 expression, attenuated hypertension, and improved cardiac function." (PMID 37034342, 2023). "Knowing that TLR4 is the major receptor for lipopolysaccharide present in Gram-negative bacteria, we can predict the influence of oral microbiota and its dysbiosis on high blood pressure." (PMID 36675104, 2023). "TLR4 overexpression aggravates vascular smooth muscle cells proliferation and vascular remodeling in the pathogenesis of hypertension." (PMID 35360231, 2022). "Our previous results confirmed that the TLR4/MyD88/NF-κB signaling pathway in the PVN regulates the downstream transcription factors of cytokines in the context of hypertension." (PMID 35204171, 2022). "Current research on the role of the TLR4/MyD88/NF‐kB axis in the PVN in cardiovascular disease has mainly focused on hypertension." (PMID 35393774, 2022).
Hypertension (continued). "Considering exercise effects on hypertension, low- and medium-intensity exercise effectively improved blood pressure through TLR4/NF-kB suppression and improved hypertension in rats." (PMID 35784579, 2022). "Recent research revealed increased TLR4 expression in spontaneously hypertensive rats (SHRs) compared to Wistar rats, while reduced hypertension and myocardial fibrosis were observed when TLR4 activity was inhibited." (PMID 35860690, 2022). "Vascular TLR4 expression is increased in cardiovascular disease, including several hypertension (SHR, Ang II infusion, DOCA-Salt), atherosclerosis, and other animal models." (PMID 35360231, 2022). "Activation of TLR4 is directly involved in vascular inflammation, vascular dysfunction, and hypertension." (PMID 35360231, 2022). "TLR4 overexpression aggravates vascular smooth muscle cells proliferation and vascular remodeling in hypertension." (PMID 35371030, 2022). "Activation of TLR4 is directly involved on vascular inflammation, vascular dysfunction, and hypertension." (PMID 35371030, 2022). "Vascular TLR4 expression is increased in cardiovascular disease, including several animal models of hypertension (SHR, Ang II infusion, DOCA-Salt), atherosclerosis and others." (PMID 35371030, 2022). "Enforced TLR-signaling (especially TLR4- and MyD88-dependend pathways) has been described in murine hypertension with a high variability in the effects depending on the investigated model." (PMID 33443617, 2021). "Beyond mechanical stress, activation of the local renin-angiotensin system and toll-like receptor 4 pathway by systemic hypertension can induce vascular inflammation and remodeling, contributing to aneurysm rupture." (PMID 34043701, 2021). "In genetic models of hypertension, spontaneously hypertensive rats showed higher cardiac TLR4 expression whereas anti-TLR4 antibody treatment decreased blood pressure." (PMID 33443617, 2021). "The interaction between the inflammatory cytokine protein, HMGB1, and TLR4, resulted in the up-regulation of NF-kB which in turn resulted in hypertension in Neuro-2a cells of mice treated with Ang II." (PMID 34489714, 2021). "In mice with NG-nitro-l-arginine methyl ester (l-NAME)–induced hypertension, blood pressure was blunted in TLR4 knockout mice compared with wild-type mice, supporting the role of TLR4—at least—in this experimental model of arterial hypertension." (PMID 33443617, 2021). "Surprisingly, we observed that unilateral microinjection of a μOR-specific agonist, DAMGO, in the NTS led to the formation of the AT1R/μOR heterodimer, and that TLR4 expression was involved in the progression of hypertension." (PMID 34829655, 2021). "In this study, we investigated the formation of the μOR/AT1R heterodimer, determined its correlation with μORs level in the NTS, and explored the role of TLR4-dependent inflammation in the development of hypertension." (PMID 34829655, 2021). "The blockade or knockdown of toll-like 4 receptor (TLR4), which is required for integral sensing and signaling of the innate system, attenuates Ang II-dependent hypertension, as well as renal and cardiac injury." (PMID 34829655, 2021). "Taken together, there is on the one hand promising murine data regarding TLR4-signaling as a potential pharmaceutical target in essential hypertension." (PMID 33443617, 2021). "A combination between HS and TLR4 was found to enhance myocardial inflammatory reaction, thereby accelerating development of hypertension." (PMID 33324685, 2020). "Chronic blockade of brain TLR4 significantly attenuated ANG II-induced hypertension and cardiac hypertrophy." (PMID 32760236, 2020). "In fact, TLR4−/− mice demonstrated full blood pressure protection against chronic endothelial nitric oxide synthase (eNOS) blockade-induced hypertension." (PMID 31694260, 2019). "Divergence of blood pressure regulation in response to pharmacological blockade or genetic deletion of Toll-like receptor 4 in animal models of hypertension." (PMID 31191352, 2019).
Hypertension (continued). "To test the effect of 8 weeks of aerobic ExT or PVN infusion of TLR4 inhibitor in hypertension, we respectively examined the PVN levels of TNF-α and IL-1β mRNA and protein by RT-qPCR, western blotting, and immunofluorescence staining." (PMID 31708733, 2019). "TLR4 expression is reported to be elevated in heart failure, hypertension, and left ventricular hypertrophy." (PMID 31336567, 2019). "TLR4 upregulation by Angiotensin II (Ang II) was shown to contribute to hypertension and vascular dysfunction through reactive oxygen species production." (PMID 31336567, 2019). "In this study, we demonstrated that aerobic ExT is beneficial for hypertension treatment through the modulation of TLR4/MyD88/NF-κB signaling in the PVN." (PMID 31708733, 2019). "Recent studies indicate that TLR-4 participates in hypertension and in the regulation of experimental renal inflammation." (PMID 31572188, 2019). "In summary, while the idea of TLR4 involvement in BP regulation is gathering broader support, we are only now uncovering pathways mediated by this receptor during hypertension." (PMID 31191352, 2019). "Evidence gathered over the past two decades has shown that Toll-like receptor 4 (TLR4) signalling is involved in several aspects of the cardiac pathological process, such as cardiac remodelling, ischaemia/reperfusion injury, hypertension, and atherosclerosis." (PMID 28698617, 2017). "Our data suggests that in C3H/HeJLps-d mice, deficiency of functional TLR4 reduces oxidative stress and macrophage activation to decrease TGF-β-induced extracellular matrix protein deposition in the kidney in Ang-II induced hypertension." (PMID 28743964, 2017). "Recent studies implicate TLR4 activation and oxidative stress in cardiovascular diseases and also as a link between inflammation and hypertension." (PMID 28743964, 2017). "This is mainly because TLR4 can respond to angiotensin II, a DAMP, and cause subsequent vascular dysfunction and high blood pressure." (PMID 28769820, 2017). "In the case of hypertension, TLR4 has been well-documented to mediate aberrant immune and inflammation in vasculature, kidneys and autonomic nervous system." (PMID 28769820, 2017). "Taken together, these data demonstrate that the action of resistin on hypertension and IR is mediated by TLR4." (PMID 26917360, 2016). "Our data showed that resistin induces both IR and hypertension in mice and these effects are TLR4-dependent." (PMID 26917360, 2016). "Nonetheless, the current data undermines the key role played by brain TLR4 signaling in the pathogenesis of hypertension and suggest that TLR4 as a novel therapeutic target for the treatment of essential hypertension." (PMID 25879545, 2015). "By contrast, no significant increase of SBP, pulse pressure or diagnosis of hypertension was observed in the 319 cases with TLR4 SNP rs4986790 across BMI quartiles." (PMID 26435700, 2015). "Nevertheless, the present findings provide strong evidence that TLR4 within the PVN plays a critical role in the pathogenesis of hypertension, at least in part, due to increased binding with its specific DAMP, HMGB1." (PMID 25879545, 2015). "But comparison of upper and lower age tertiles identified a significant association of the TLR4 SNP rs4986790 with SBP, pulse presser and hypertension." (PMID 26015800, 2015). "The role of brain TLR4 has been recently suggested to modulate cardiac remodeling in heart failure rats and hypertension." (PMID 25811788, 2015). "Given that the TLR4 blockade reduces MAP, it can be postulated that TLR4 plays role in hypertension, possibly via HMGB1." (PMID 25879545, 2015). "Given the role of PVN in initiation of high blood pressure, it is imperative to investigate the role of TLR4 within the PVN in modulating inflammatory response in hypertension." (PMID 25879545, 2015). "Taken together, the current findings suggest the role of brain TLR4 in cardiac hypertrophy in hypertension." (PMID 25879545, 2015).
Hypertension (continued). "Overall, our data for the first time demonstrate that an excessive increase in TLR4 within the PVN plays an important role in initiation of the inflammatory process observed in essential hypertension." (PMID 25879545, 2015). "Nonetheless, the results of the present study suggest that activation of TLR4 in the PVN of the brain leads to increased sympathetic activation in an animal model of essential hypertension." (PMID 25879545, 2015). "The results of this study suggest that increased expression of TLR4, which is associated with increased RAS activity, contributes to the occurrence of hypertension." (PMID 25093580, 2014). "In conclusion, TLR4 pathway activation due to increased RAS activity is involved in hypertension, and by inducing oxidative stress, this pathway contributes to the endothelial dysfunction associated with this pathology." (PMID 25093580, 2014). "In conclusion, this study demonstrates, for the first time, that the increased RAS activity observed in hypertension stimulates the TLR4 pathway, contributing to the occurrence of hypertension." (PMID 25093580, 2014). "Altogether, this study suggests for the first time, to the best of our knowledge, that TLR4 contributes to the endothelial dysfunction observed in hypertension." (PMID 25093580, 2014). "Eissler and colleagues observed an increased hypertension-related expression of TLR4-mediated signalling pathway in vascular cells of untreated hypertensive rats." (PMID 25120286, 2014). "In short, high-salt diets cause ecological imbalances that damage the intestinal barrier, allowing LPS to cross into the bloodstream and activate the inflammatory pathway mediated by TLR4, ultimately triggering a systemic inflammatory disease mechanism including hypertension." (PMID 41373978, 2025). "Interestingly, out of line with apoptosis, pyroptosis predominantly regulates excessive cell growth in hypertension instead of cell death, involving TLR4 and NF‐κB signals in the rapid proliferation of VSMCs in hypertension development." (PMID 38873710, 2024). "Levels of the lipopolysaccharide (LPS) endotoxin, involved in the pathogenesis of hypertension for its ability to activate the Toll-like receptor 4 (TLR4) with production of proinflammatory cytokines, chemokines, and ROS in CNS, decreased in the kefir-treated SHR rats." (PMID 37512959, 2023). "Interestingly, toll like receptor 4 (TLR4) is a major receptor that responds to LPS and has recently been shown to be elevated during hypertension in the brain and vasculature." (PMID 37034342, 2023). "Moreover, TLR4 contributes to endothelial dysfunction observed in hypertension, and anti-TLR4 treatment improves endothelium-dependent relaxation." (PMID 35488354, 2022). "Toll-like receptor 4 (TLR4) has been shown to be upregulated under hypertension." (PMID 35860690, 2022). "TLR4 is the most well defined TLR in the pathogenesis of hypertension." (PMID 36369944, 2022). "Increased expression of TLR4 is related to development and maintenance of hypertension." (PMID 35860690, 2022). "An overview regarding all different TLRs and their impact on arterial hypertension has been described in detail before, so we focus on TLR4 and the partially contradictory findings for its role in murine models of arterial hypertension and discuss the sparse human data." (PMID 33443617, 2021). "Therefore, we investigated the progression of hypertension after the activation of microglia and TLR4, the effects of TLR4 inhibitor TAK242 on SBP, the phosphorylation of nNOSS1416, and the activity of the microglia." (PMID 34829655, 2021). "Considering the alleged role played by TLR4 in BP modulation in animal models of hypertension, we sought to investigate whether systemic blockade of this receptor with a neutralising TLR4 antibody would impact MAP in STZ-induced diabetic animals." (PMID 32694567, 2020).
Hypertension (continued). "Collectively, this study reveals that ExT could attenuate RSNA and blood pressure, and inhibit TLR4/MyD88/NF-κB signaling in the PVN of 2K1C hypertension." (PMID 31708733, 2019). "Out of thirteen characterized TLRs, TLR4 is the most explored in hypertension." (PMID 31191352, 2019). "Further, a recent study suggests resistin contribute to hypertension via TLR4 signalling." (PMID 31053755, 2019). "In SHR, a genetic model of hypertension with both neural and vascular alterations, our group previously reported similar effects regarding lowering BP after long-term treatment with an anti-TLR4 antibody." (PMID 31191352, 2019). "TLR4 blockade was performed locally, systemically, and centrally, aiming at understanding its roles in the labyrinth of pathways that are disrupted during hypertension." (PMID 31191352, 2019). "A western blot analysis was performed to assess the role of TLR4 and inflammation in hypertension." (PMID 28225018, 2017). "TLR4 is a putative resistin receptor; therefore, TLR4 knockout (tlr4−/−) mice were used to determine whether resistin induces hypertension and IR through TLR4." (PMID 26917360, 2016). "To determine the effect of TLR4 blockade within the PVN on inflammatoy response in hypertension, we examined the levels of pro-inflammatory cytokines (PICs), TNF-α and IL-1β mRNA and protein levels in the PVN by real time RT PCR and western immunoblot, respectively." (PMID 25879545, 2015). "Recent evidence suggests that central blockade of TLR4 could improved myocardial inflammation and attenuated cardiac function in angiotensin II-induced hypertension." (PMID 26133371, 2015). "In this study, we aim to investigate the role of TLR4 in the PVN of SHR rats, a model of human essential hypertension, and evaluate if the TLR4 blockade within the PVN has any protective role in hypertension, cardiac function, inflammatory cytokines in the brain and plasma, and sympathetic activity." (PMID 25879545, 2015). "Our current results together with previous reports suggest role of TLR4 in hypertension." (PMID 25879545, 2015). "Moreover, it is well known that the PVN is central in initiation and development of hypertension, the role of TLR4 within the PVN of genetic model of human essential hypertension has never been investigated before." (PMID 25879545, 2015). "Animal data gives first evidence that TLR4 signaling might contribute to chronic low-grade inflammation, which influence SBP increase and hypertension-associated cardiac remodeling." (PMID 26015800, 2015). "Interestingly TLR4 G polymorphism shows a significant association for SBP (p = 0.017), hypertension (p < 0.001) and pulse pressure (p = 0.026) only in the upper age tertile (age ≥70 and <80 years)." (PMID 26015800, 2015). "More importantly, inhibition of TLR4 by bilateral microinjection into the PVN of the SHR rats delays the progression of hypertension; reduces cardiac hypertrophy; attenuates PICs, iNOS, and NFκB, as well as NE levels; and improves anti-inflammatory IL-10 levels within the PVN." (PMID 25879545, 2015). "TLR4 may have a role in the development of several cardiovascular diseases; however, little is known about its participation in hypertension." (PMID 25093580, 2014). "Immunofluorescence and western immunoblot analyses revealed that hypertension contributed to the activation of TLR4 and NF-κB, accompanied by significantly enhanced expression of proinflammatory mediators, such as tumor necrosis factor-α (TNF-α), interleukin-1β (IL-1β), and interleukin-18 (IL-18)." (PMID 24223475, 2013). "In contrast, chronic hypertension induced higher TLR4 expression in these regions (hypertension)." (PMID 24223475, 2013). "Increased oxidative stress and reduced NO bioavailability are important contributing factors and are closely related with inflammatory signaling pathways such as toll like receptor 4 signaling in the pathogenesis of endothelial dysfunction, hypertension, and cardiovascular and renal diseases." (PMID 24385682, 2013).